HFE (homeostatic iron regulator)
Diseases named in the same sentence as HFE in open-access papers (continued):
Sharing a sentence is not in itself a finding about the gene and the disease.
prostate carcinoma (3 papers, 2012 to 2017). A carcinoma that arises from epithelial cells of the prostate gland. "To better understand the roles of HFE and TUSC3 in prostate cancer, we used small interfering RNAs (siRNAs) to silence their expression in PC-3 cells, and evaluate the consequences of loss of HFE or TUSC3 function on cell proliferation and migration." (PMID 29088772, 2017). "Vitamin D treatment inhibited HFE mRNA expression, and down-regulation of HFE by transfecting small interfering RNA suppressed PC-3 human prostate cancer cell proliferation and wound healing ability." (PMID 29088772, 2017). "The associations of HFE rs9393682 and TUSC3 rs1378033 with disease progression were replicated across both stages of the study for localized and advanced prostate cancer, respectively." (PMID 29088772, 2017). "HFE has been recognized as a receptor for β2-microglobulin (β2-M), and β2-M is a known growth-promoting gene for several human cancers, including prostate cancer." (PMID 29088772, 2017). "The associations of HFE rs9393682 and TUSC3 rs1378033 with prostate cancer progression was replicated across both cohorts, which would reduce false-positive findings in this study." (PMID 29088772, 2017). "Since β2-M interacts with HFE to mediate its cellular processes 4, we knocked down HFE in ARCaPM prostate cancer cells using lentiviral shRNA particles." (PMID 23874600, 2013). "In this study, we demonstrate the role of β2-M and its binding partner, HFE, in modulating radiation sensitivity and chemo-sensitivity of prostate cancer." (PMID 23874600, 2013). "According to multivariate analyses adjusted for known predictors, HFE rs9393682 was found to be associated with disease progression for localized prostate cancer, and TUSC3 rs1378033 was associated with progression for advanced prostate cancer in both cohorts." (PMID 29088772, 2017). "We then assessed HFE and TUSC3 expression using a prostate cancer complementary DNA array containing 39 tissue samples." (PMID 29088772, 2017). "This study shows that HFE rs9393682 and TUSC3 rs1378033 influence TTP in patients with prostate cancer." (PMID 29088772, 2017). "The expression of two genes near these VDRE SNPs, HFE and TUSC3, can be regulated by 1,25-VD, suggesting that HFE and TUSC3 might be potential vitamin D target genes and thus contribute to prostate cancer progression." (PMID 29088772, 2017). "The effects of 1,25-VD on the mRNA expression levels of HIST1H1C, HFE, SGCZ, TUSC3, and CYP24A1 (cytochrome P450 family 24 subfamily A member 1), a well-known 1,25-VD target gene, were examined using quantitative real-time polymerase chain reaction (qRT-PCR) in PC-3 human prostate cancer cells." (PMID 29088772, 2017).
amyotrophic lateral sclerosis (2 papers, 2009 to 2023). Amyotrophic lateral sclerosis (ALS) is a neurodegenerative disease characterized by progressive muscular paralysis reflecting degeneration of motor neurons in the primary motor cortex, corticospinal tracts, brainstem and spinal cord. "Polymorphisms in the major histocompatibility complex class 1-like gene known as HFE have been proposed as genetic modifiers of amyotrophic lateral sclerosis (ALS), Alzheimer's disease (AD), Parkinson's disease (PD), and stroke." (PMID 19228389, 2009).
astrocytoma (2 papers, 2009 to 2014). "We have previously reported that human neuroblastoma cells and human astrocytoma cells lines expressing commonly occurring polymorphisms in the HFE gene were resistant to chemotherapy and radiation." (PMID 25255031, 2014). "In the present study, we used astrocytoma cell lines that we identified with the HFE gene variants and TMZ resistance to screen compounds from DIVERSet compound library from Chembridge (San Diego, CA) and found a number of effective compounds with a similar chemotype." (PMID 25255031, 2014). "We investigated the mRNA levels of hepcidin (HAMP), HFE, neogenin (NEO1), transferrin receptor 1 (TFRC), transferrin receptor 2 (TFR2), and hemojuvelin (HFE2) in normal human brain, brain tumors, and astrocytoma cell lines." (PMID 19386095, 2009). "The present study describes the expression of several iron-related genes including hepcidin (HAMP), HFE, neogenin(NEO1), transferrin receptor 1 (TFRC), transferrin receptor 2 (TFR2), and hemojuvelin(HFE2) in normal human brain, brain tumors, and astrocytoma cell lines." (PMID 19386095, 2009).
Cluster headache (2 papers, 2024 to 2025). A type of headache characterized by repeated attacks of unilateral pain lasting 15 to 180 minutes and associated with local autonomic signs. "Mutations in the HFE gene have also recently been associated with cluster headaches and could be implicated in the prevalence of pain in CF." (PMID 40225935, 2024).
cognitive decline (2 papers, 2007 to 2024). "In summary, we have found the HFE polymorphisms to significantly modify the association between lead burden and the rate of cognitive decline." (PMID 17687449, 2007). "Even though the association of lead burden with cognitive decline among men with only HFE wild-type alleles appeared linear (optimal degree of smoothing: 1, p = 0.72), the association appeared curvilinear, specifically, steeper with greater lead burden in the variant allele carriers." (PMID 17687449, 2007).
distal intestinal obstruction syndrome (2 papers, 2024). "There are the data HFE gene mutations are related to the development of meconium ileus and hepatic pathology in cystic fibrosis." (PMID 39881831, 2024). "The mutations C282Y and H63D in the HFE protein were associated with increased rates of CF-related diabetes (CFRD), meconium ileus (MI), and distal intestinal obstruction syndrome (DIOS)." (PMID 40225935, 2024).
fibrosis (2 papers, 2019 to 2020). the formation of excess fibrous connective tissue in an organ or tissue in a reparative or reactive process. "HFE knockout and DTg mice displayed similar extent of iron overload and of fibrosis." (PMID 31717526, 2019).
gout (2 papers, 2019). A condition characterized by painful swelling of the joints, which is caused by deposition of urate crystals. "Our PheWAS indicates HFE C282Y is associated with arthrosis, coxarthrosis, osteoarthritis, and gout, and HFE H63D is associated with ankylosing spondylitis and has a suggestive association with dorsalgia." (PMID 31226389, 2019). "Moreover, the results of the “single-SNP” and “leave-one-out” analyses showed that rs7965584 in the RP11-654D12.2 gene and rs1800562 in the HFE gene corresponded to Mg and Fe, respectively, and had a significant impact on gout." (PMID 30759836, 2019).
iron (2 papers, 2020 to 2025). "Similarly, SNPs in genes regulating iron homeostasis, such as HFE and TF, could interact with high vitamin C intake to exacerbate oxidative damage through increased ROS production and iron overload in renal tissues." (PMID 40514697, 2025).
iron refractory iron deficiency anemia (2 papers, 2016 to 2020). "Two of these modifier genes are HFE (H= high FE = Fe, iron homestasis regulator) related with type 1 hemochromatosis and TMPRSS6 (transmembrane serine protease 6) coding for the matriptase 2 and causative of iron refractory iron deficiency anemia (IRIDA)." (PMID 32349426, 2020).
lung carcinoma (2 papers, 2019). "We determined the prevalence of HFE variants and their impact on cancer phenotypes in lung cancer cell lines, in lung cancer patient specimens, and using The Cancer Genome Atlas (TCGA) database." (PMID 31856248, 2019). "In summary, these data suggest that there is a sexually dimorphic effect of HFE polymorphisms in the survival and metastatic disease in lung cancer." (PMID 31856248, 2019). "We determined the frequency of HFE gene variants in lung cancer patients (adenocarcinoma of the lung, squamous cell lung cancer) seen in our Penn State Hershey Medical Center (PSHMC), and publically available lung cancer databases." (PMID 31856248, 2019). "As far as we know, this is the first report for the impact of HFE variants and sex on lung cancer patients’ outcome." (PMID 31856248, 2019). "We evaluated the association between HFE genotype and HFE mRNA expression in TCGA lung cancer data." (PMID 31856248, 2019). "We found 7 of 10 lung cancer cell lines had the H63D or C282Y variant of the HFE gene." (PMID 31856248, 2019). "The prevalence of two common HFE gene variants (H63D, C282Y) has been studied in many cancer types; however, the impact of HFE variants, sex and HFE gene expression in lung cancer has not been studied." (PMID 31856248, 2019). "We further compared the survival of lung cancer patients based on HFE expression and sex." (PMID 31856248, 2019). "HFE genotype and metastasis rate based on sex of lung cancer patients at PSHMC." (PMID 31856248, 2019). "Although we found HFE genotype and sex effect for lung cancer patient’s survival and metastatic disease, this is not related with the frequency of HFE genotype/alleles." (PMID 31856248, 2019). "In the present study, the level of HFE gene expression was not different between WT HFE and HFE variants of lung cancer patients (matched normal, primary tumors) in TCGA lung cancer data." (PMID 31856248, 2019). "In general, the survival curve between males and females was not different regardless of HFE expression levels in lung cancer patients." (PMID 31856248, 2019). "The polymorphisms in HFE, TFR1 and TF (rs1799945, rs3817672 and rs1049296, respectively) did not appear to be correlated with lung cancer in our study." (PMID 30640897, 2019). "In addition, HFE gene expression level did not impact survival of TCGA lung cancer patients (LUAD, LUSC) even when stratified for sex." (PMID 31856248, 2019). "The survival pattern was not different regardless of HFE expression levels in lung cancer patients." (PMID 31856248, 2019). "The level of HFE expression was not different between males and females in matched normal or primary tumors of LUAD and LUSC lung cancer patients in two sample t-test." (PMID 31856248, 2019).
neuroblastoma (2 papers, 2009 to 2014). Neuroblastoma (NB) is the most common solid, extracranial childhood tumor. "We screened a panel of cytokines and trophic factors using a multiplexed immunoassay in human neuroblastoma SH-SY5Y cells expressing different variants of HFE." (PMID 19228389, 2009).
oral cancer (2 papers, 2007 to 2015). "Taken together with the fact that the HFE protein mediates intestinal iron uptake, we hypothesized that the C282Y and H63D polymorphisms are associated with increased oral cancer risk." (PMID 26690219, 2015). "To determine whether there is an increased risk of oral cancer in individuals with HFE mutations, we genotyped the C282Y and H63D polymorphisms in a case-control study of 301 oral cancer cases and 437 healthy controls." (PMID 26690219, 2015). "Future studies examining individuals with HFE gene polymorphisms and clinically elevated iron levels should be conducted in order to better estimate how HH and iron levels may affect oral cancer risk." (PMID 26690219, 2015). "The lack of association between HFE polymorphisms and oral cancer may indicate that there is not enough iron deposition in the relevant tissues to cause the cellular injuries that lead to neoplasia." (PMID 26690219, 2015).
sickle cell anaemia (2 papers, 2016 to 2025). "Results of this study showed that HFE gene mutations are important in iron deposition in the liver in patients with sickle cell disease." (PMID 27095682, 2016). "HFE gene mutations are effective on iron deposition in the liver in sickle cell disease patients." (PMID 27095682, 2016).
viral hepatitis (2 papers, 2021 to 2024). An acute or chronic inflammation of the liver parenchyma caused by viruses. "Some researchers concur that polymorphisms of the HFE gene play a significant role in iron deposition, and therefore in the simultaneous progression of viral hepatitis." (PMID 34582652, 2021).
viral infections (2 papers, 2017 to 2024). "However, various HFE mutations as seen in HH patients suggest that HFE dysregulation contributes strongly to the particular phenotype seen in viral infections." (PMID 28769934, 2017). "In addition to virus infection, the iron metabolism-related gene HFE can also bind to MAVS for SQSTM1/p62-mediated MAVS degradation via selective autophagy." (PMID 38965634, 2024).
abscesses (1 paper, 2019). "The association between HFE C282Y and higher risk of cellulitis, abscesses, furuncles and curbuncles, subcutaneous infections as well as osteomyelitis provides further evidence that genetically elevated iron levels are associated with higher infection risk." (PMID 31226389, 2019).
atherosclerosis (1 paper, 2022). A disease characterized by the build-up of fatty material and calcium deposition in the arterial wall resulting in partial or complete occlusion of the arterial lumen. "It is reasonable to believe that “an increase in atherosclerosis” should not have been observed in HH if there is not excess iron accumulation in the aortic tissues or if sequence variations in HFE gene cannot initiate excess iron accumulation in the aortic tissues." (PMID 35669479, 2022).
Autoimmunity (1 paper, 2017). The occurrence of an immune reaction against the organism's own cells or tissues. "Furthermore, HFE has also been described as a skin tolerance antigen in pre‐clinical models, with implications in autoimmunity." (PMID 28474781, 2017). "The most obvious implications of HFE as a negative regulator/inhibitor of MHC I antigen presentation and CD8+ lymphocyte activation are related to the immune response during infections, cancer immune surveillance, and autoimmunity." (PMID 28474781, 2017).
biliary tract cancer (1 paper, 2025). "Interestingly, the variants in HFE, APOE, and TERT displayed concordant effects on HCC and biliary tract cancer." (PMID 40823170, 2025).
cardiomyopathy (1 paper, 2023). A disease of the heart muscle or myocardium proper. "Animal models of iron excess, such as mice lacking the HFE protein, are more sensitive to cardiac damage after DOX therapy, indicating a connection between iron metabolism and DOX-induced cardiomyopathy." (PMID 37298779, 2023).
chronic kidney disease (1 paper, 2024). Impairment of the renal function secondary to chronic kidney damage persisting for three or more months. "While PPI network analysis identified six interacting genes, only HFE has established links to both chronic kidney disease and sepsis." (PMID 39086896, 2024).
erythrocytosis (1 paper, 2021). "The association between the HFE variants and the development of erythrocytosis is not clearly understood." (PMID 34349782, 2021).
glioblastoma (1 paper, 2016). The most malignant astrocytic tumor (WHO grade IV). "Similarly, polymorphisms in HFE have been shown to correlate with decreased survival in several forms of brain tumors, including both glioblastoma and metastatic brain tumors." (PMID 27898674, 2016). "It is not clear why iron-regulating gene function fails to differentiate long- and short-term survivors in glioblastoma multiforme, especially considering the evidence that polymorphisms in a single iron-regulatory gene, HFE, may decrease survival in GBM." (PMID 27898674, 2016).
head and neck cancer (1 paper, 2015). A primary or metastatic malignant neoplasm affecting the head and neck. "HFE polymorphisms were unrelated to head and neck cancer risk." (PMID 26690219, 2015). "While altered iron status has been linked to head and neck cancer development, no studies on the possible impact of HFE polymorphisms have been reported to date." (PMID 26690219, 2015).
hepatitis C (1 paper, 2024). "Therewith, a relative association has been found between some sorts of chronic liver diseases like non-alcoholic steatohepatitis and hepatitis C with human homeostatic iron regulator protein (HFE: High Fe2+) gene mutations." (PMID 39050104, 2024).
idiopathic pulmonary fibrosis (1 paper, 2019). Idiopathic pulmonary fibrosis (IPF) is a nonneoplastic pulmonary disease that is characterized by the formation of scar tissue within the lungs in the absence of any known cause. "Finally, patients with idiopathic pulmonary fibrosis (IPF), a restrictive lung disease with a prominent gas diffusion limitation, have a higher frequency of HFE allelic variants associated with the iron overload disease hemochromatosis, when compared to healthy controls." (PMID 30609678, 2019).
large cell lung cancer (1 paper, 2019). "Only 1 large cell lung cancer cell line did not have a HFE gene variant and the only squamous cell carcinoma cell line was heterozygote for C282Y." (PMID 31856248, 2019).
metastatic disease (1 paper, 2019). "There are significant HFE genotype and sex differences for survival and metastatic disease." (PMID 31856248, 2019).
Myocardial fibrosis (1 paper, 2021). "According to the first theory, the lack of HFE gene function directly impacts myocardial fibrosis." (PMID 34359361, 2021).
neuropathy (1 paper, 2020). A disorder affecting the nervous system that manifests with pain, tingling, numbness, and/or muscle weakness. "We found that measures indicating higher systemic iron at the cellular level or higher systemic iron stores, as well as the minor HFE gene variant were associated with delayed onset of neuropathy among PWH on cART." (PMID 33057367, 2020). "The lack of association between systemic iron stores and onset of neuropathy when self-reported non-whites were included in our analyses might be explained by the much lower frequency of HFE variants and/or higher inflammation in these individuals." (PMID 33057367, 2020).
periodontitis (1 paper, 2024). An acute or chronic inflammatory process that affects the tissues that surround and support the teeth. "The allele frequencies at the mutation loci of LFNG, LENG8, NPHS1, HFE, ILDR1, and DMXL2 genes were analyzed in the 15 patients with severe periodontitis." (PMID 37435641, 2024).
primary Sjögren syndrome (1 paper, 2025). "This case describes a 39-year-old woman with primary Sjögren syndrome (pSS) and heterozygosity for the HFE H63D mutation who developed PCT following hydroxychloroquine (HCQ) therapy." (PMID 40821324, 2025).
prostate tumors (1 paper, 2018). "Analysis of these genes in patient samples from the TGCA dataset using the MethHC database (methhc.mbc.nctu.edu.tw) confirmed significant hypermethylation of the DKK3, PTGS2, SLC16A5, HFE, and CYP27A1 promoters in prostate tumors, compared to normal prostate." (PMID 29843383, 2018).
red blood cell disorders (1 paper, 2012). "Rare mutations in many loci associated with HbA1c (SPTA1ANK1HK1TMPRSS6) are known to cause hereditary red blood cell disorders and common variants at several loci (SPTA1, HFE, ANK1HK1TMPRSS6) are associated with hematological traits like hemoglobin concentration and mean corpuscular volume." (PMID 22540250, 2012).
renal cell carcinoma (1 paper, 2013). "Moreover, HFE was also overexpressed in other cancers including brain, and renal cell carcinomas." (PMID 23991213, 2013).
retinal degeneration (1 paper, 2018). Degeneration of the retina. "We have previously reported that HFE is expressed predominantly in the basolateral membrane of the retinal pigment epithelium, and HFE knockout (KO) mice accumulate iron in the retina with significant retinal degeneration by 18 months of age36." (PMID 29445185, 2018).
sarcopenia (1 paper, 2019). Progressive decline in muscle mass due to aging which results in decreased functional capacity of muscles. "HFE C282Y homozygosity is associated with substantial excess sarcopenia, frailty, and chronic pain at older ages." (PMID 30657865, 2019). "It is interesting to note that models suggest that targeted population screening for the HFE C282Y homozygous status would be cost effective, even before our new findings reported substantial later life sarcopenia, frailty, and chronic pain." (PMID 30657865, 2019).